ARHGAP15 (Rho GTPase activating protein 15)
Diseases named in the same sentence as ARHGAP15 in open-access papers (continued):
Sharing a sentence is not in itself a finding about the gene and the disease.
tumor (9 papers, 2018 to 2025). "We found that in the low-score group, ARHGAP15 tumour cells and CD8 + CCL5 immune cells were significantly colocalized, indicating good spatial consistency, according to the spatial transcriptome sequencing (ST-seq) data." (PMID 38730464, 2024). "According to the single-cell sequencing results, most of the tumour cells in both the low- and high-score groups were ARHGAP15 and TPK1 cells, respectively." (PMID 38730464, 2024). "Conversely, genes involved in cell death (Aifm3, FC = –1.9, P = 0.04) or tumor suppression (SerpinB2, FC = –35.0, P = 7 × 10–4; Arhgap15, FC = –3.6, P = 0.03; Frk, FC = –1.7, P = 0.01) were downregulated." (PMID 36892943, 2023). "Fisher’s exact test showed that ARHGAP15 expression was significantly correlated with clinical stage (P = 0.005), tumor size (P = 0.028), metastasis (P = 0.020), and vital status (P = 0.010)." (PMID 29867200, 2018). "ARHGAP15 expression was significantly correlated with clinical stage, tumor size metastasis, vital status, and overall survival of CRC patients." (PMID 29867200, 2018). "On balance, ARHGAP15 served as a tumor suppressor to suppress the growth and metastasis of CRC cells." (PMID 29867200, 2018). "Additionally, a Rho GTPase activating protein 15 (ARHGAP15) inhibits Rac1 activity and reduces intracellular ROS accumulation, thereby improving the antioxidant capacity of tumor cells during oxidative stress." (PMID 41188920, 2025). "Additionally, the colony formation ability of single tumor cell was critical to develop metastasis in a secondary site and we demonstrated that upregulation of ARHGAP15 enhanced the colony formation capability of single tumor cell under oxidative stress." (PMID 36802400, 2023). "Collectively, these data implied the protective effect of ARHGAP15 on circulating tumor cells might be related with regulation of ROS." (PMID 36802400, 2023). "Furthermore, it was also demonstrated that ARHGAP15 expression in the primary tumor tissue was significantly upregulated in the GC patients with LN metastasis compared with those without LN metastasis." (PMID 36802400, 2023). "ARHGAP15, induced via androgen, plays a tumor suppressor role." (PMID 34307347, 2021). "In summary, these results suggest that ARHGAP15 might serve as a tumor suppressor during CRC progression and metastasis through PTEN/AKT/FOXO1-signaling pathway." (PMID 29867200, 2018). "Furthermore, ARHGAP15 overexpression significantly decelerated the pace of tumor growth and metastasis in the lung in vivo." (PMID 29867200, 2018). "Collectively, ARHGAP15 overexpression significantly decelerated the pace of tumor growth in vivo." (PMID 29867200, 2018). "In addition, ARHGAP15 overexpression significantly decelerated the pace of tumor growth and metastasis in the lung in vivo." (PMID 29867200, 2018). "All of these data indicate that ARHGAP15 acts as a tumor suppressor in CRC." (PMID 29867200, 2018). "In addition, ARHGAP15 expression was significantly correlated with clinical stage, tumor size metastasis, vital status, and overall survival of CRC patients." (PMID 29867200, 2018). "Furthermore, we found that GC cells with ectopic expression of ARHGAP15 were enriched in metastatic lymph nodes, which might explain the higher abundance of ARHGAP15 in metastatic lymph nodes than the primary tumor." (PMID 36802400, 2023). "Further studies indicated that ARHGAP15 suppressed RAC1 and then decreased intracellular reactive oxygen species produced by NOX2, a downstream gene of RAC1, thus protecting colonizing tumor cells from oxidative stress." (PMID 36802400, 2023). "In this study, we found ARHGAP15 inhibited the activity of RAC1 to alleviate intracellular ROS accumulation, thus protecting tumor cells from oxidative stress induced cell death." (PMID 36802400, 2023).
tumor (continued). "Remarkably, in the TCGA‐LGG and GTEx cohorts, a significant majority of the ARHGAP family genes, with the exception of ARHGAP15, ARHGAP20, ARHGAP24, and ARHGAP28, exhibited notable differential expression between tumour tissues and normal samples, as established through Wilcoxon test analysis." (PMID 39075640, 2024). "Here, ARHGAP15, a Rho GAP, was believed to play a tumor suppressive role." (PMID 36802400, 2023). "Mechanistically, ARHGAP15 inactivated RAC1 and then decreased intracellular accumulation of reactive oxygen species (ROS), thus enhancing the antioxidant capacity of colonizing tumor cells under oxidative stress." (PMID 36802400, 2023). "In addition, the tumor cells were labelled with GFP prior to tail vein injection so that they could be quantified by flow cytometry, the result of which also suggested that ARHGAP15 overexpression enhanced early seeding and survival of GC cells in murine lungs." (PMID 36802400, 2023).
cancer (4 papers, 2018 to 2023). A tumor composed of atypical neoplastic, often pleomorphic cells that invade other tissues. "This study deciphered the underlying mechanism between metastasis and oxidative stress, and it opened a potential new avenue for cancer treatment by targeting ARHGAP15 or its downstream signaling with pro-oxidant in the future." (PMID 36802400, 2023). "ARHGAP15 immunoreactivity was frequently detected in the cytoplasm of carcinoma cells, and was positively correlated with that of Rac1 and androgen receptor labeling index." (PMID 29534468, 2018). "This may help explain the contradictory role of ARHGAP15 in cancer metastasis under different circumstances." (PMID 36802400, 2023). "Five hypermethylated regions were in genes previously associated with cancer (TRAP1, SLC38A3, CHRM1, EDN2, and PROX1), while six hypomethylated regions were in genes previously associated with cancer (NUMBL, ALDH1B1, FTCD, FASTKD2, FAM96A, and ARHGAP15)." (PMID 36474183, 2022). "Comparing HCC in the choline deficient model and choline supplemented model, significant methylation differences were seen in 11 genes previously associated with cancer (hypermethylation of TRAP1, SLC38A3, CHRM1, EDN2, and PROX1; hypomethylation of ALDH1B1, FTCD, FASTKD2, FAM96A, and ARHGAP15)." (PMID 36474183, 2022). "ARHGAP15 immunoreactivity was detected in the cytoplasm of carcinoma cells." (PMID 29534468, 2018). "Knockdown of ARHGAP15 resulted in activation of PAK1/2 and indirectly promoted Rac activation, thereby enhancing cancer-promoting signal transduction." (PMID 36168627, 2022).
ARHGAP15 also shares sentences with these, for which no sentence is quoted: depression (2 papers); pancreatic cancer (2); alcohol dependence (1); allergic rhinitis (1); atherosclerosis (1); atopic eczema (1); autism (1); bipolar disorder (1); colon cancer (1); Crohn disease (1); epilepsy (1); hematologic disorder (1); infection (1); inflammatory bowel disease (1); insomnia (1); lung carcinoma (1); lung injury (1); lymph node metastasis (1); memory impairment (1); metastatic cancer (1); migraine without aura (1); neuroblastoma (1); neurological diseases (1); periodontitis (1); psychiatric disorder (1); ulcerative colitis (1).